FOS (Fos proto-oncogene, AP-1 transcription factor subunit)
Diseases named in the same sentence as FOS in open-access papers (continued):
Sharing a sentence is not in itself a finding about the gene and the disease.
Osteoblastoma (continued). "FOS rearrangements were present in 94% of osteoid osteomas and osteoblastomas, with a concordance of 86% between FISH and immunohistochemistry." (PMID 31768625, 2020). "Both NF2 and FOS are involved in regulating bone homeostasis, thereby providing a mechanistic link to the excessive bone growth of osteoblastoma." (PMID 32542935, 2020). "In a follow-up study, immunohistochemistry showed strong and diffuse nuclear staining in the majority (79%) of osteoid osteomas and osteoblastomas, using a FOS antibody against the N terminus." (PMID 31741049, 2020). "By immunohistochemical analysis, 60–80% of osteoblastomas show increased FOS expression, which can be used as a reliable marker in routine clinical diagnostics." (PMID 32542935, 2020). "Second, we scored FOS overexpression as strong and diffuse (> 50% of tumor cells) nuclear expression that we found in all 22 osteoid osteomas and in 12 of 21 osteoblastomas." (PMID 31768625, 2020). "One conventional osteoblastoma displayed a novel mechanism of FOS upregulation; bringing the entire FOS gene under the control of the WNT5A enhancer that is itself activated by FOS." (PMID 32542935, 2020). "Osteoid osteoma and osteoblastoma are bone-forming tumors shown to harbor FOS (87%) and FOSB (3%) rearrangements." (PMID 31768625, 2020). "Strong nuclear expression of FOS in > 50% of the tumor cells was observed in all osteoid osteomas (22/22), in 57% of osteoblastomas (12/21) and in 3/197 control cases." (PMID 31768625, 2020). "To summarize, FOS immunohistochemistry can be used as an auxiliary tool for osteoid osteoma and osteoblastoma in short decalcified tissue, while FOSB immunohistochemistry is diagnostically not useful." (PMID 31768625, 2020). "To conclude, in short decalcified biopsies, FOS immunohistochemistry can be used to diagnose osteoid osteoma and osteoblastoma, as overexpression is seen in the majority, being rare in their mimics." (PMID 31768625, 2020). "In this study, we evaluated the utility of the use of immunohistochemistry of FOS to diagnose osteoid osteoma and osteoblastoma." (PMID 31768625, 2020). "Strong and diffuse nuclear staining for FOS was observed in all osteoid osteomas (22/22), in 57% of the osteoblastomas (12/21), and in one case with reactive callus formation (1/3)." (PMID 31768625, 2020). "In this study, a striking difference between osteoid osteoma and osteoblastoma samples for FOS expression was noticed, as all osteoid osteoma, but only 57% of osteoblastomas showed positivity." (PMID 31768625, 2020). "All three samples demonstrated strong nuclear FOS immunoreactivity, supporting the notion that alterations in FOS or FOSB underpin every case of osteoblastoma and osteoid osteoma." (PMID 29858576, 2018). "Consistent with this prediction, we observed intense nuclear immunoreactivity of FOS in osteoblastoma cells." (PMID 29858576, 2018). "Recently, recurrent translocations in FOS and FOSB have been detected in osteoblastoma, as well as osteoid osteoma, and may be of diagnostic value." (PMID 40506925, 2025). "Since FOS plays a role in osteogenic differentiation, the effect of FOS truncation on osteogenic differentiation and proliferation was investigated in an in vitro model for osteoid osteoma and osteoblastoma." (PMID 41424327, 2025). "Tumor cells were positive for c-FOS, a marker of osteoblastoma and cementoblastoma." (PMID 38589906, 2024). "Thus, by combining both approaches, 85% of the osteoblastomas analyzed showed evidence of FOS rearrangement." (PMID 35347251, 2022). "Notably, five FOS/FOSB-negative osteoblastomas coming from the study of Lyskjaer9 were also properly positioned within the osteoblastoma cluster." (PMID 35347251, 2022). "Of these, the osteoblastoma case already showed a FOS rearrangement." (PMID 31768625, 2020).
Osteoblastoma (continued). "Under these circumstances, the use of FISH for FOS could be diagnostically useful, for cases where it is difficult to distinguish osteoid osteoma and osteoblastoma from their histologic mimics." (PMID 31768625, 2020). "Taken together, our findings indicate that FOS and FOSB alterations may be exploited as diagnostic markers for osteoblastoma and osteoid osteoma." (PMID 29858576, 2018). "Besides, tumor cells were positive for c-FOS, a marker of osteoblastoma and cementoblastoma." (PMID 38589906, 2024). "Rearrangements in FOS, and less frequently FOSB, have recently been identified in osteoid osteoma and osteoblastoma." (PMID 41424327, 2025). "Cancer genomics efforts over the past decade have revealed that somatic rearrangements in FOS and FOSB underpin osteoblastoma, osteoid osteoma, epithelioid haemangioma and pseudomyogenic haemangioendothelioma." (PMID 36426824, 2023). "Whereas immunohistochemistry is not specific for an underlying translocation and can be influenced by tissue preservation, a smaller fraction of osteoblastomas are characterized by homozygous NF2 deletion and lack FOS/FOSB rearrangements." (PMID 35347251, 2022). "We compared immunohistochemistry of FOS and FOSB between osteoid osteoma and osteoblastoma and other lesions with bone deposition." (PMID 31768625, 2020). "The discovery of FOS and FOSB rearrangements found in osteoid osteoma and osteoblastoma have not only given insight in tumorigenesis, but have also provided the bone tumour pathologist with a novel diagnostic tool to improve diagnostic accuracy." (PMID 31741049, 2020). "Recently, recurrent translocations in FOS (87%) and FOSB (3%) were found in osteoblastoma and osteoid osteoma." (PMID 31768625, 2020). "Here, we report recurrent rearrangement of FOS and its paralogue, FOSB, in the most common benign tumours of bone, osteoblastoma and osteoid osteoma." (PMID 29858576, 2018). "Our key finding was recurrent, disease-defining structural variation of the FOS and FOSB oncogenes in osteoblastoma and osteoid osteoma." (PMID 29858576, 2018). "Although FOS and FOSB mutations are frequent findings in osteoblastoma, they do not underlie all cases." (PMID 32542935, 2020). "Novel FOS and FOSB rearrangements were recently found in osteoid osteoma and osteoblastoma." (PMID 31741049, 2020). "In 2018, in a quiet genomic background with paucity of somatic alterations, recurrent FOS and—to a lesser extent—FOSB rearrangements were found in both osteoid osteoma and osteoblastoma using RNA sequencing, demonstrating that both tumours were similar at the molecular level." (PMID 31741049, 2020). "In rare cases of osteoma morphologically mimicking osteoblastoma, additional IHC or FISH testing for FOS can rule out osteoblastomas that are known to harbour FOS rearrangements." (PMID 31838586, 2020). "Moreover, previous studies described osteoblastomas rich in epithelioid appearing cells that did not carry FOS/FOSB gene fusions." (PMID 35347251, 2022). "However, a previously published small study cohort demonstrated that osteoid osteoma and osteoblastoma lacked strong nuclear expression of FOS, indicating variability in sensitivity between different antibodies." (PMID 31741049, 2020). "Finally, we could not find similar FOS and FOSB rearrangements in whole-genome sequences in 2652 non-osteoblastoma tumours." (PMID 29858576, 2018).
cervical cancer (15 papers, 2010 to 2025). A primary or metastatic malignant neoplasm involving the cervix. "The development of cervical cancer cells can be promoted by the modulation of c-FOS and cJUN proteins." (PMID 35672846, 2022). "It implies that ERs-related genes (ATF4 and DDIT3) and downstream apoptosis genes (JUN, FOS, BBC3, and PMAIP1) are the potential targets of 20(S)-GRh2 and might be interacting with each other to be involved in the apoptosis induction in cervical cancer cells." (PMID 36431966, 2022). "Combined protein–protein interaction network, hub gene screening, and qPCR validation data showed that ERs-related genes (ATF4 and DDIT3) and the downstream apoptotic genes (JUN, FOS, BBC3, and PMAIP1) were potential novel targets of 20(S)-GRh2-inducing cervical cancer cell apoptosis." (PMID 36431966, 2022).
Cognitive impairment (15 papers, 2020 to 2025). Abnormal cognition is characterized by deficits in thinking, reasoning, or remembering. "The administration of FOS can improve cognitive impairments and pathological alterations in AD mice, as well as restore the disrupted microbial composition." (PMID 39036341, 2024). "FOS treatment ameliorated cognitive deficits and pathological changes in the Tg mice." (PMID 39036341, 2024). "The significant increase in c-FOS expression and the normalization of cortisol and serotonin levels in treated rats underscore the potential of targeted light therapy in managing conditions related to sleep deprivation and possibly other cognitive impairments." (PMID 38903600, 2024). "Decreases in c-FOS expression are not always associated with cognitive impairments." (PMID 36311860, 2022).
liver cancer (15 papers, 2018 to 2025). An epithelial or non-epithelial malignant neoplasm that arises from the liver. "FOS may be the risk gene for liver cancer by playing important roles in MAPK and GPCR pathways." (PMID 32280695, 2020). "Although no experimental data pertaining to AGAP11 have been reported in the field of cancer, there is evidence to suggest that closely related genes, namely, LPL, MMP9, SGK1, TLR4, and FOS play certain roles in liver cancer through different mechanisms." (PMID 36726348, 2023). "Over 50% of key targets, such as PTGS2, FOS, were involved in Hepatitis B, MAPK signaling pathways, which were closely associated with liver cancer." (PMID 37861529, 2023). "In our present study, FOS gene exhibits the highest prediction accuracy of liver cancer among the significant nodes in network, which suggests the potential diagnostic and therapeutic implication of FOS in liver cancer." (PMID 32280695, 2020). "Collectively, our study demonstrates that FOS is a potential prognostic marker for liver cancer that may reveal a novel therapeutic avenue in this lethal disease." (PMID 32280695, 2020). "However, the role of FOS gene in liver cancer remains largely unclear." (PMID 32280695, 2020). "FOS could be considered to be a candidate gene for diagnosis and therapy for liver cancer." (PMID 32280695, 2020). "Zuogui Pill can improve different clinical symptoms in treating liver cancer, by regulating multiply targets like PTGS2 and FOS, participating in MAPK, IL-17 and TNF signaling pathways." (PMID 37861529, 2023). "Finally, in invasive liver cancers, the levels of positive regulators of SERPINB2, such as TAL1 (Z-score = 3.982, p-value = 0.237), FOSL1 (Z-score = 1.483, p-value = 0.0311) and FOS (Z-score = 3.214, p-value = 0.0347), were increased." (PMID 30965654, 2019). "Furthermore, by examining these signaling networks, we discovered that FOS (Fos proto-oncogene, AP-1 transcription factor subunit), LAMC2 (laminin subunit gamma 2), and CALML3 (calmodulin like 3) were the most significant gene nodes with high degrees involved in liver cancer." (PMID 32280695, 2020).
Stroke (15 papers, 2013 to 2025). Sudden impairment of blood flow to a part of the brain due to occlusion or rupture of an artery to the brain. "FOS is also a potential biomarker for target therapy in prevention of stroke among hypertensive patients." (PMID 38818568, 2024). "There were also significant differences in the expression of FOS in the peripheral blood of stroke patients." (PMID 34744970, 2021).
Hypertension (14 papers, 2013 to 2025). The presence of chronic increased pressure in the systemic arterial system. "Among the 34 BP signature genes (at Bonferroni corrected p<0.05), only FOS and PTGS2 have been previously implicated in hypertension." (PMID 25785607, 2015). "FOS has been shown to be activated in response to cardiovascular stress, such as hypertension." (PMID 39069811, 2025). "The occurrence of hypertensive disorder complicating pregnancy can be caused by the decrease of the expression of MMP9 in the network, and AKT1, ESR1, FOS, VEGFA and other proteins play an important role in the pathogenesis of hypertensive disorder complicating pregnancy, such as preeclampsia." (PMID 34062719, 2021). "Therefore, Fos/FOS may play an important role in the transformation of hypertension to stroke and the regulation of gene expression in IS and may be further used as a biomarker and potential therapeutic target for pre-stroke prevention and stroke prognosis." (PMID 34744970, 2021). "Oral supplement to HFD, but not ND offspring, at 6 or 8 weeks with FOS (4 g/kg/day) and L.gasseri (3 × 106 CFU/mL/day), given alone or together, appreciably protected the adult offspring from programmed hypertension and the increases in plasma NE level and sympathetic outflow." (PMID 36296991, 2022).
Hypoglycemia (14 papers, 2012 to 2025). A decreased concentration of glucose in the blood. "In contrast, the present study has demonstrated that hypoglycemia causes an increase in expression of FOS despite the death of EHNs, suggesting a protective role of FOS against hypoglycemia." (PMID 31728912, 2019). "Although the present study has confirmed the neuronal death in response to direct hypoglycemia, an exceptional phenomenon was observed which is an inverse relationship between FOS expression and glucose concentrations in the EHNs." (PMID 31728912, 2019). "Confocal imaging of triple fluorescent labeled material in fasted, insulin-injected CX3CR1+/gfp mice (microglia reporter strain on C57BL/6 background) revealed close apposition of microglia and hypoglycemia-activated, c-FOS positive neurons." (PMID 30996341, 2019). "Confocal microscopic analysis of hypothalamic sections revealed that IBA1 positive microglia are recruited in close apposition to hypoglycemia-activated c-FOS positive, NPY neurons." (PMID 30996341, 2019). "83% of all activated (c-FOS) positive neurons contained Npy mRNA, while only 4% of activated neurons expressed Pomc mRNA in response to hypoglycemia." (PMID 30996341, 2019). "Overnight fasting and insulin induced-hypoglycemia resulted in coexpression c-FOS and OREXIN-A in perifornical part of the lateral hypothalamus." (PMID 30996341, 2019). "We demonstrated that hypoglycemia modulates the expression of hypothalamic miRNAs that are related to FOS and FTO." (PMID 31728912, 2019). "FOS expression was significantly increased in response to hypoglycemia suggesting a protective role in this condition." (PMID 31728912, 2019). "It is noteworthy that there was an overlap in the miRNAs between FTO and FOS despite the fact that both had differential responses to hypoglycemia." (PMID 31728912, 2019). "Taking into account the previous findings, it is crucial to investigate the molecule signature of hypoglycemia and the expression of hypothalamic miRNAs, FOS and FTO simultaneously to propose novel biomarkers for HAAF." (PMID 31728912, 2019). "Administration of anti-miR-9 markedly reversed the expression of FOS under hypoglycemia; however, it remains unclear whether FOS expression enhances EHN viability in response to hypoglycemia." (PMID 37108651, 2023). "Conversely, hypoglycemia significantly increased FOS expression and reduced FTO expression." (PMID 37108651, 2023). "In addition, FOS expression has been shown to decrease within the medial and dorsal hypothalamic areas in response to hypoglycemia." (PMID 31728912, 2019). "Taking into account this finding, we can suggest that the noticeable increase in FOS expression in response to hypoglycemia may result from the inhibition of miRNAs expression." (PMID 31728912, 2019). "Twelve miRNAs that are related to both FOS and FTO were identified and the expression of ten of them was reduced significantly in response to hypoglycemia." (PMID 31728912, 2019). "This interrelationship between the hypothalamic miRNAs and the regulatory protein, FOS and FTO, in response to hypoglycemia facilitates an opportunity to identify potential biomarkers and novel therapeutic targets for HAAF." (PMID 31728912, 2019). "Previously, changes of FOS expression in response to hypoglycemia were used to determine the location of the neurons that are functionally related to hypoglycemia without in-depth studies about the molecular aspects of FOS expression during the process of neuronal death." (PMID 31728912, 2019).
leukemia (14 papers, 2012 to 2025). A malignant (clonal) hematologic disorder, involving hematopoietic stem cells and characterized by the presence of primitive or atypical myeloid or lymphoid cells in the bone marrow and the blood. "FOS OE significantly reduced leukemia burden in recipient mice and markedly prolonged their overall survival." (PMID 40093906, 2025). "In our 3D BM niche-like AML model, leukemia cells demonstrated an upregulation of FGF2, FOS, and ERBB2, which acts on and activates Twist1 and Snail2." (PMID 37932837, 2023). "ScRNA-seq reveals an expression pattern with high FOS and JUN at leukaemia evolution, which resolves following therapy but reoccurs following relapse and death." (PMID 33441952, 2021). "Rothem et al26 have reported that reduced expression of transcription factors as CREB1, ATF1, USF1, FOS, JUN, Sp3, and Sp1 is responsible for a major decrease in RFC mRNA expression in the CCRF‐CEM and derived human leukemia cell lines." (PMID 32614991, 2020). "In our study, AP1(FOS and JUN) expression is negatively regulated during leukemia progression." (PMID 38461240, 2024).
myeloma (13 papers, 2007 to 2025). "For example, it has been reported that c‐FOS/c‐JUN activity is altered in almost all MM patients and plays a major role in a transcriptional network associated with myeloma survival." (PMID 37581569, 2023). "Co‐occupancy of IKZF1 and c‐FOS on the same consensus in ∼50% of target genes strongly suggests that the two factors form a complex on the myeloma genome." (PMID 37581569, 2023). "In addition to the demethylase activity, KDM6B upregulates the expression of the MAPK signaling pathway components including ELK1 and FOS and then mediates the growth and survival of multiple myeloma cells." (PMID 35783266, 2022). "Collectively, our data suggest that c‐FOS is an integral component of the IKZF1 complex in MM cells and primarily mediates activator functions of the complex via direct binding to IKZF1 on the myeloma genome." (PMID 37581569, 2023). "Because the binding sequence of c‐FOS on the myeloma genome is different from common AP‐1‐binding motifs, such as TPA‐responsive elements and cAMP‐responsive elements, it is highly possible that c‐FOS binds to DNA through protein‐protein interactions with IKZF1." (PMID 37581569, 2023). "Left panel: In multiple myeloma (MM), IKZF1/3 binds to the canonical IKZF‐binding motif CTTCC in a complex with c‐FOS/c‐JUN to activate the transcription of genes involved in the growth and survival of MM cells such as interferon regulatory factor 4 (IRF4) and SLAMF7." (PMID 37581569, 2023).